ENSG00000281295
Gene: Small nucleolar RNA gene on chromosome 22 (33,704,786 to 33,704,922, reverse strand). Ensembl gene ENSG00000281295.
Gene Ontology:
Biological process: RNA processing
Cellular component: nucleolus
Homologues: Orthologues: mouse Gm55812 (75% identical). Paralogues in human: SNORA50A (65% identical).